TIGIT (T cell immunoreceptor with Ig and ITIM domains)
Diseases named in the same sentence as TIGIT in open-access papers (continued):
Sharing a sentence is not in itself a finding about the gene and the disease.
type 1 diabetes (7 papers, 2018 to 2026). "Teplizumab-induced partial exhaustion of CD8+ T memory cells (KLRG1+TIGIT+) has been associated with a positive clinical response to teplizumab in stage 2 type 1 diabetes." (PMID 39560746, 2025). "In the context of type 1 diabetes, persistent hyperglycemia may directly impair the most functionally suppressive TIGIT+ Treg subset, which plays a role in maintaining peripheral tolerance." (PMID 41597269, 2026). "Therefore, we sought to understand how CD226 and TIGIT impact central and peripheral tolerance mechanisms in the context of type 1 diabetes." (PMID 33013915, 2020). "In conclusion, the extended analysis of the validation cohort confirms that CXCR5−PD-1hi Tph cells are increased in the blood of children with type 1 diabetes and suggests that TIGIT may be a useful auxiliary marker to define circulating Tph cells." (PMID 31270583, 2019). "Thus, the lower level of TIGIT expression in CD57+CD4+ T cells of children developing type 1 diabetes may contribute to the disease progression." (PMID 38714671, 2024). "Thus, the decreased levels of TIGIT in cytotoxic CD57+CD4+ T cells of children who later develop type 1 diabetes may play a role in the disease progression." (PMID 38714671, 2024). "However, TIGIT KO showed minimal impact on type 1 diabetes incidence." (PMID 33013915, 2020). "While the roles of CD226 and TIGIT in type 1 diabetes pathogenesis remain unclear, blockade of CD226 has been shown to protect from experimental autoimmune encephalitis (EAE), another autoimmune mouse model in which disease pathogenesis is thought to be primarily T cell-mediated." (PMID 33013915, 2020). "Our initial analyses indicate that TIGIT, an immunomodulatory receptor also expressed at high levels by CXCR5+PD1hi Tfh cells in blood and tonsils, shows promise as a candidate auxiliary marker for the identification of potentially pathogenic Tph cells in individuals with type 1 diabetes." (PMID 31270583, 2019). "Enhancement of CD8+ T cell pathogenicity by dual TIGIT and CD96 blockade could therefore be expected to augment type 1 diabetes development in NOD mice." (PMID 33013915, 2020).
allergic disease (6 papers, 2018 to 2025). An immune response that occurs following re-exposure to an innocuous antigen, and that requires the presence of existing antibodies against that antigen. "However, the physiological importance of TIGIT+ ILC2s in chronic allergy remains to be elucidated in RUNX-competent mice." (PMID 37036426, 2023). "Moreover, a previous study demonstrated that TIGIT enhances Th2 immunity in mice with experimental allergic diseases." (PMID 36741366, 2022). "In addition, a study has also shown that TIGIT enhanced TH2 immunity in mice with experimental allergic disease through interaction with CD155 expressed in dendritic cell." (PMID 35844584, 2022). "Thus, TIGIT might also be useful as a therapeutic target in allergic diseases." (PMID 36741366, 2022). "In this study, the impact of elevated levels of TIGIT cannot be ruled out, the role of TIGIT in T cell apoptosis and allergic diseases, and whether TIGIT interacts with CD226 and affects CD226 function, should be explored in future studies." (PMID 39349422, 2024). "However, whether TIGIT plays a regulatory or stimulatory role in chronic allergy has not yet been determined." (PMID 37036426, 2023).
follicular lymphoma (6 papers, 2021 to 2025). Follicular lymphoma is a form of non-Hodgkin lymphoma characterized by a proliferation of B cells whose nodular structure of follicular architecture is preserved. "Similarly, TIGIT expression is associated with T-cell suppression and exhaustion, which predicts clinical outcomes and responses to anti-PD-1 therapies in follicular lymphoma." (PMID 40458414, 2025). "In follicular lymphoma, increased numbers of TIGIT+ T cells are associated with poor survival, therefore TIGIT may serve as a predictive marker for therapeutic clinical outcomes." (PMID 36159789, 2022). "A previous meta-analysis of cancers demonstrated that a high TIGIT expression is correlated with worse OS and PFS, and in hematological malignancies, high TIGIT expression is associated with poor clinical outcomes in patients with follicular lymphoma and AML." (PMID 35625835, 2022). "In conclusion, increased numbers of TIGIT+ T cells were correlated with inferior outcomes and poor survival and the blockade of TIGIT signaling may have therapeutic potential for patients with follicular lymphoma." (PMID 35474948, 2022). "The abundantly tumor‐infiltrating TIGIT+ Tregs showed enhanced suppressive capacity by inhibiting the activation and proliferation of CD8+ T cells in patients with follicular lymphoma." (PMID 35474948, 2022). "have demonstrated that abundantly tumor‐infiltrating TIGIT+ Tregs show enhanced suppressive capacity by inhibiting the activation and proliferation of CD8+ T cells in patients with follicular lymphoma." (PMID 35474948, 2022). "In follicular lymphoma (FL) patients, TIGIT is highly expressed on intratumoral Treg and late-stage memory CD8+T cells, and increased numbers of TIGIT-expressing tumor infiltrating T cells reveal a correlation with poor survival rate." (PMID 33670993, 2021).
Hodgkins lymphoma (6 papers, 2018 to 2022). A heterogeneous group of malignant lymphoid neoplasms of B-cell origin characterized histologically by the presence of Hodgkin and Reed-Sternberg (HRS) cells in the vast majority of cases. "In conclusion, our preliminary results in Hodgkin lymphoma, demonstrated a mutually exclusive expression of TIGIT in peritumoral lymphocytes and PD-L1 in HRS cells, with an overlap in cases with low level of TIGIT reactivity." (PMID 33782477, 2021). "Our results encourage further studies evaluating the role of TIGIT as a target for immunotherapies in Hodgkin’s lymphoma." (PMID 30514251, 2018). "Studies showed that 68-84% of T cells had co-expression of TIGIT and PD-1 in hodgkin lymphoma (HL)." (PMID 36605439, 2022). "Variable expression of PD-1 and TIGIT was observed on CD3+ T cells in patients with Hodgkin lymphoma, suggesting that TIGIT blockade alone or in combination with other drugs might be used as a potential therapeutic target." (PMID 32117298, 2020). "In conclusion, TIGIT expression is highly variable between patients with Hodgkin’s lymphoma." (PMID 30514251, 2018). "As to yet, data on the possible role of TIGIT in Hodgkin’s lymphoma are lacking." (PMID 30514251, 2018).
lymph node metastasis (6 papers, 2021 to 2024). "Interestingly, lymph node metastasis was associated with the overexpression of various checkpoints, including PD-L2, TIGIT, TIM-3, ICOS, PD-L1, and CD27." (PMID 33414407, 2021). "Similarly, ICI effectiveness, including PD1, CTLA4, and TIGIT, was higher in the group with lymph node metastasis than in the non‐metastasis group." (PMID 39206584, 2024). "TIGIT could activate its ligand CD155,232 and the activation of TIGIT/CD155 signaling was associated with the pathologic grade and lymph node metastasis of HNSCC." (PMID 35474948, 2022). "TIGIT+ Tregs could activate its ligand CD155, and the activation of TIGIT/CD155 signaling was associated with the pathologic grade and lymph node metastasis of HNSCC." (PMID 35474948, 2022). "As per multivariate analysis, in addition to lymph node metastasis and elevated CEA, high expressions of CD155 and TIGIT were independent prognostic predictors in patients with CRC." (PMID 35324958, 2022). "ICI marker analysis indicated that the lymph node metastasis group exhibited non‐significant differences in immune checkpoint gene expression levels, except for PD1, TIGIT, and CTLA4, which were significantly higher than those in the non‐metastasis group (p = 0.0008, p = 0.0004, p = 0.0093)." (PMID 39206584, 2024). "Indeed, tumor-resident NK cells from patients with lymph node metastases manifest a higher presence of TIGIT than those from patients with no lymph node metastases." (PMID 38893211, 2024).
mesothelioma (6 papers, 2021 to 2025). A usually malignant and aggressive neoplasm of the mesothelium which is often associated with exposure to asbestos. "In an epithelioid mesothelioma model, anti-PD-1 plus anti-TIGIT induced stronger and more durable anti-tumor responses than either chemotherapy or dual anti-PD-1 plus CTLA-4 therapy." (PMID 41463268, 2025). "The ongoing pan-tumour investigation into anti-TIGIT efficacy and the promising translational research reported here in mesothelioma, suggests that TIGIT remains a potentially highly promising target." (PMID 39939955, 2025). "We then demonstrate in a mouse model of mesothelioma that the combination of anti-PD-1 and anti-TIGIT elicits an enhanced anti-tumour response compared to clinical standard-of-care therapies (anti-PD-1 + CTLA-4 combination and chemotherapy)." (PMID 39939955, 2025). "As this novel immune checkpoint remains largely unexplored in mesothelioma, we will discuss the potential of TIGIT blockade as an alternative therapeutic approach for MPM." (PMID 35327475, 2022). "Functionally, the expression of TIGIT was associated with TIL hypofunction, suggesting that an anti-TIGIT therapy may have potential for therapeutic use in mesothelioma, and a number of clinical trials and anti-TIGIT therapies are in progress." (PMID 33952230, 2021). "Additional inhibitory checkpoints under investigation include TIM-3 and TIGIT, both of which are being evaluated in clinical trials for advanced solid tumors, though mesothelioma-specific data are not yet available." (PMID 41463268, 2025). "In this consideration, besides anti-PD-1, other immune checkpoint inhibitors such as anti-BTLA, anti-CTLA-4, anti-Siglec-10, anti-TIGIT, anti-TIM-3, anti-LAG-3 could be tested in combination to investigate their suitability for enhancing Vδ2 T cell efficacy in this mesothelioma model." (PMID 38077396, 2023).
metastatic tumors (6 papers, 2019 to 2025). "In advanced metastatic disease, second-generation immune checkpoint inhibitors (e.g., TIGIT, LAG3, TIM3) added to an ICI and anti-VEGF backbone suggests the future of first-line HCC treatment is moving towards triplet systemic therapy." (PMID 39858016, 2025). "TIM-3 and TIGIT were significantly expressed on CD4eff in metastatic tumors compared with the other tissue types, whereas PD-1 and CTLA-4 expressions were significantly lower in PBMC." (PMID 35320356, 2022). "The majority of studies investigating TIGIT expression in TME across different malignancies have shown its negative impact on overall survival, progression-free survival, disease-free survival, recurrence-free survival, or its association with increased hazard for metastatic disease." (PMID 37109579, 2023). "Interestingly, the transcription factor YAP1 consistently showed low expression levels irrespective of the sample type, whereas TIGIT, an immune checkpoint that plays a pivotal role in immune suppression, was overexpressed in the vast majority of both primary and LN metastatic tumors." (PMID 40107154, 2025). "The number of IDO positive cells was not significantly higher in metastatic tumors (P = 0.079), but the number of IDO and TIGIT positive cells/mm2 correlated in both hot spots (R2 = 0.24, P < 0.01) and full tumor sections (R2 = 0.35, P < 0.01)." (PMID 30993893, 2019).
prostate carcinoma (6 papers, 2019 to 2024). A carcinoma that arises from epithelial cells of the prostate gland. "Recently, TIGIT expression has been implicated in failures of prostate cancer checkpoint inhibition." (PMID 30988330, 2019). "Our results reveal that the combined use of inhibitors directed against the IL6R/STAT-3 axis and TIGIT enhances the functional activity of NK cells against castration-resistant prostate cancer cells." (PMID 35465350, 2022). "However, no studies have currently reported using a strategy to combat prostate cancer using both blockade of TIGIT and the disruption of the IL6R/STAT-3 axis." (PMID 35465350, 2022). "Also, the combined use of Stt, Tcz, and anti-TIGIT increased the functional capacity of NK cells against DU145 castration-resistant prostate cancer cells." (PMID 35465350, 2022). "Therefore, this study determines if the combined blockade of IL6R/STAT-3 and TIGIT enhances NK cell cytotoxicity against prostate cancer cells." (PMID 35465350, 2022). "Finally, the disruption of the IL6R/STAT-3 axis in prostate cancer cells and the blocking of TIGIT on NK-92 were observed to increase the cytotoxicity of NK-92 cells against DU145 cells through an increase in sFasL, granzyme A, granzyme B, and granulysin." (PMID 35465350, 2022). "This combined expression of CD155 and other checkpoint ligands may prove to be an important variable that might help predict TIGIT blockade efficacy and thus enable the suitable selection of patients with advanced prostate cancer most likely to benefit from such a treatment." (PMID 35465350, 2022). "Therefore, we explored the expression of inhibitory receptors in CD8+ T cells in prostate cancers including PD-1, LAG3, TIM-3, TIGIT, and BTLA." (PMID 32850758, 2020). "We find upregulation of TIGIT—a marker of T cell exhaustion during masculinizing GAHT—in vivo, but we also find induction of TNF responses and IFNγ responses by NK cells, which seems at odds with reported impairments of TH1 responses in male prostate cancer patients." (PMID 39232147, 2024). "Likewise, we determined that using these treatments in combination with anti-TIGIT increases and maintains the expression of some factors such as NKp46 and secretion of granzyme A, granzyme B, perforin, and granulysin which may regulate cytotoxicity against DU145 prostate cancer cells." (PMID 35465350, 2022).
renal clear cell carcinoma (6 papers, 2022 to 2025). "We aim to identify the critical role of TIGIT in renal clear cell carcinoma and find potential targeted TIGIT drugs." (PMID 37035135, 2023). "However, the role of TIGIT in normal organ tissues and renal clear cell carcinoma is unclear." (PMID 37035135, 2023). "In renal clear cell carcinoma, TRPV3 can induce the expression of immune checkpoints such as LAG3, CTLA4, PDCD1, and TIGIT, leading to the accumulation of immunosuppressive T cells in the tumor microenvironment." (PMID 41331166, 2025).
sarcoma (6 papers, 2021 to 2024). A usually aggressive malignant neoplasm of the soft tissue or bone. "In addition, it has been shown that the cytokine IL-15 modulates the balance between activation and exhaustion by simultaneously promoting cytotoxic function and inducing the expression of inhibitory TIGIT on NK cells in patients with sarcomas." (PMID 38967649, 2024). "Finally, the results of immune checkpoints’ expression showed significant differences in CD274, HAVCR2, PDCD1, and TIGIT between the two subtypes, and m7GRGs might be a predictive marker for the treatment of sarcomas by targeting immune checkpoints." (PMID 36816047, 2023).
urothelial cancer of the bladder (6 papers, 2021 to 2025). "Kyrollis Attalla has identified TIM-3 and TIGIT as promising targets for monotherapy or combination therapy with other immune checkpoint inhibitors in patients with urothelial cancer of the bladder." (PMID 38172792, 2024). "Kyrollis Attalla has identified TIM-3 and TIGIT as viable targets for monotherapy or in conjunction with other immune checkpoint inhibitors in patients with urothelial cancer of the bladder." (PMID 37664033, 2023). "Moreover, Kyrollis Attalla has identified TIM-3 and TIGIT as promising targets for monotherapy or combination therapy with other immune checkpoint inhibitors in patients with urothelial cancer of the bladder." (PMID 37780567, 2023). "In patients with bladder urothelial carcinoma, Kyrollis Attalla discovered TIM-3 and TIGIT as viable targets for monotherapy or in conjunction with other immune checkpoint inhibitors." (PMID 37377916, 2023).
endometrial cancer (5 papers, 2021 to 2025). Primary or metastatic malignant neoplasm involving the endometrium (mucous membrane that lines the endometrial cavity). "One study in endometrial cancer linked resident tumour NK cell expression of TIGIT to disease severity." (PMID 34830795, 2021). "Consistent with a recent study on endometrial cancer, high PD-1 and TIGIT expression levels indicate that CD103+CD8+ T cells are promising targets for ICIs." (PMID 39391310, 2024). "Furthermore, tissue-resident memory T cells co-expressing PD-1 and TIGIT in endometrial cancer show reduced cytotoxicity and tumor targeting; yet, they paradoxically maintain enhanced proliferation, potentially contributing to their persistence within the tumor." (PMID 41300994, 2025).
experimental autoimmune encephalomyelitis (5 papers, 2019 to 2023). An autoimmune demyelinating disease of the central nervous system that is produced experimentally in animals by the injection of homogenized brain or spinal cord in Freund's adjuvant. "TIGIT−/− mice were more susceptible to the induction of experimental autoimmune encephalomyelitis." (PMID 35844584, 2022). "There are no data on the role of TIGIT in MS, but Tigit-overexpressing transgenic mice or mice treated with a TIGIT agonistic antibody had reduced experimental autoimmune encephalomyelitis (EAE) induction, whereas TIGIT-deficient mice were more susceptible to EAE." (PMID 31134049, 2019). "TIGIT knock-out mice are more susceptible to the development of spontaneous experimental autoimmune encephalomyelitis (EAE), suggesting an important role for the CD226/TIGIT pathway in autoimmune responses." (PMID 34298735, 2021).
fibrosarcoma (5 papers, 2014 to 2023). A malignant mesenchymal fibroblastic neoplasm affecting the soft tissue and bone. "In support of this notion, combined TIGIT and CD96 blockade has shown increased efficacy at preventing tumor growth via a CD8+ T cell-mediated mechanism in a mouse fibrosarcoma model in comparison to either antibody alone." (PMID 33013915, 2020).
mantle cell lymphoma (5 papers, 2022 to 2024). Mantle cell lymphoma is a rare form of malignant non-Hodgkin lymphoma affecting B lymphocytes in the lymph nodes in a region called the ``mantle zone''. "Acquired TIGIT expression in TCs with mantle cell lymphoma relapse enhances the interaction of TIGIT+ TCs with monocyte CD155/PVR 44, suggesting that a rational strategy could be considered for targeting TIGIT to enhance the anti-tumor immunotherapy efficacy." (PMID 37649613, 2023). "Moreover, evidence suggests that TIGIT is highly expressed in mantle cell lymphoma cells in patients after relapse, and cotargeting TIGIT prevented CAR-T cell relapses, thereby promoting the long-term PFS of mantle cell lymphoma patients." (PMID 37670328, 2023).
uveal melanoma (5 papers, 2019 to 2025). A melanoma derived from melanocytes of the uveal tract. "The expression of immune checkpoint receptor TIGIT is increased in primary uveal melanomas that seed metastases, and correlates with the expression of checkpoint receptor IDO." (PMID 30993893, 2019). "The TIGIT gene presented a significant prognostic action only in uveal melanoma." (PMID 39064019, 2024). "Similarly, in uveal melanoma (UVM) and liver hepatocellular carcinoma (LIHC), CRABP2 expression is significantly correlated with seven of these immune checkpoint genes (LAG3, CTLA4, PDCD1LG2, HAVCR2, PDCD1, CD274, and TIGIT)." (PMID 39991584, 2025). "Additionally, concerning immunosuppressive gens, PLAG1 was significantly positively correlated with TIGIT, CD96, and CD244 in LGG, uveal melanoma, and liver hepatocellular carcinoma, indicating that it may facilitate the formation of a tumor immune-suppressive microenvironment." (PMID 40276502, 2025).